EML4 (EMAP like 4)
Diseases named in the same sentence as EML4 in open-access papers (continued):
Sharing a sentence is not in itself a finding about the gene and the disease.
acute leukemia (1 paper, 2020). A clonal (malignant) hematopoietic disorder with an acute onset, affecting the bone marrow and the peripheral blood. "In the next step, we sought to identify f-circRNAs based on actual BioProject RNA-Seq data at the example of H3122 cells, an NSCLC cell line harbouring the EML4-ALK fusion (BioProject ID PRJNA350335) and of various acute leukemia samples with PML-RARα fusion gene (BioProject ID PRJNA315254)." (PMID 32470133, 2020).
appendicitis (1 paper, 2016). Acute inflammation of the vermiform appendix. "During a one-month interruption of crizotinib treatment due to appendicitis, the EML4-ALK rearrangement was detected in her platelets but was lost when she reinitiated crizotinib treatment." (PMID 26544515, 2016).
carcinosarcoma (1 paper, 2022). A malignant tumor composed of a mixture of carcinomatous and sarcomatous elements. "Only one early-stage patient with non-ACA histology (carcinosarcoma) had an EML4–ALK fusion (variant 1, E13; A20)." (PMID 36293366, 2022).
gliosarcoma (1 paper, 2020). A rare histological variant of glioblastoma (WHO grade IV) characterized by a biphasic tissue pattern with alternating areas displaying glial and mesenchymal differentiation (WHO). "In case 2, Oncomine Comprehensive v3 analysis of the local left frontal gliosarcoma recurrence detected an EML4:NTRK3 fusion, a CDKN2A/B loss and an MRE11A alteration of unknown significance." (PMID 33353026, 2020).
hyperplasia (1 paper, 2021). An abnormal increase in the number of cells in an organ or a tissue with consequent enlargement. "Hyperplasia was only correlated to MANF and EML4 according to the MS/MS analysis." (PMID 35008858, 2021).
hypothyroidism (1 paper, 2024). Abnormally low levels of thyroid hormone. "EML4 fusion was also linked with surgical procedure type and smaller tumor size, as well as the history of hypothyroidism." (PMID 39409115, 2024).
infertile (1 paper, 2022). "Spermatozoa from the homozygous EML5R1654W mutant bull and an infertile bull with stump tails localized EML4 to the sperm head (acrosomal and post-acrosomal region, respectively)." (PMID 35478957, 2022).
interstitial lung disease (1 paper, 2024). A diverse group of lung diseases that affect the lung parenchyma. "Inclusion: advanced NSCLC, EGFR wild type and EML4-ALK fusion-negative, ECOG 0–1.Exclusion: symptomatic central nervous system metastases, use of corticosteroids,* interstitial lung disease or active infection." (PMID 38886117, 2024).
large cell carcinoma (1 paper, 2013). A malignant epithelial neoplasm composed of large, atypical cells. "Three of these five EML4-ALK fusion containing tumors were adenocarcinomas and two were large cell carcinomas." (PMID 23484153, 2013).
Lymphadenopathy (1 paper, 2015). Enlargement (swelling) of a lymph node. "Furthermore, compared to patients with EGFR mutations, lymphadenopathy was more common and remarkable in patients with EML4-ALK gene fusions in our study." (PMID 26332764, 2015).
mucinous adenocarcinoma (1 paper, 2023). An invasive adenocarcinoma composed of malignant glandular cells which contain intracytoplasmic mucin. "EML4‐ALK fusion gene was mainly detected in invasive adenocarcinoma (7/9), 3 cases were adherent growth type, 2 cases were acinar‐like growth type, 1 case was solid‐like growth type and 1 case was mucinous adenocarcinoma." (PMID 37340599, 2023).
neuroendocrine carcinoma (1 paper, 2022). A malignant neuroendocrine neoplasm composed of cells containing secretory granules that stain positive for NSE and chromogranin. "An LCNEC and AC showed an EML4-ALK fusion, and the high-grade neuroendocrine carcinoma, a KLC1-ALK fusion." (PMID 35756632, 2022).
Neuroepithelial Tumor (1 paper, 2020). "We present a unique and challenging case of a high-grade neuroepithelial tumor with echinoderm microtubule-associated protein-like 4-anaplastic lymphoma kinase (EML4-ALK) fusion in a five-month-old child." (PMID 32685319, 2020).
pericardial effusion (1 paper, 2022). Fluid collection within the pericardial sac, usually due to inflammation. "On the contrary, EML4-ALK (exon 6: exon 20) were found only in pericardial effusion-sDNA." (PMID 35646096, 2022). "Among the 6 actionable alterations, EML4-ALK (exon 20: exon 20) fusion, ERBB2 Y772_A755dupYVMA and KRAS G12C showed a consistency of 100% between PE-cfDNA and pericardial effusion." (PMID 35646096, 2022). "Among them, EGFR T790M, EGFR E746_A750delELREA, EGFR L861Q, KRAS G12C, EML4-ALK (exon 18: exon 20) fusion, EML4-ALK (exon 20: exon 20) fusion, and ERBB2 Y772_A755dupYVMA were detected in both pericardial effusion-cfDNA and pericardial effusion-sDNA." (PMID 35646096, 2022). "Among the actionable alterations, MET amplification exhibited the highest population frequency, while EGFR E746_A750delELREA, EGFR T790M, EML4-ALK (exon 20: exon 20) fusion, and KRAS G12C displayed a 100% consistency between the tumor tissue and pericardial effusions." (PMID 35646096, 2022).
pneumonitis (1 paper, 2025). An inflammatory process affecting the lung parenchyma. "We present a patient with echinoderm microtubule-associated protein-like 4 (EML4) and ALK fusion protein-positive mNSCLC who developed severe hypoxemia and pneumonitis requiring intubation within 2 days of initiating brigatinib therapy." (PMID 40342820, 2025).
preeclampsia (1 paper, 2025). Preeclampsia is a hypertensive disorder of pregnancy that is characterized by new-onset hypertension with proteinuria presenting after 20 weeks of gestation, and depending on mild or severe forms may initially present with severe headache, visual disturbances, and hyperreflexia. "The literature supports consistent changes in ApoB, Sod2, and EML4 trends with the results of this study, confirming a potential relationship between the therapeutic effects of SA on preeclampsia and the PI3K/Akt/eNOS pathway." (PMID 40717981, 2025). "Loss of MAP4 results in the loss of PI3Kα targeting and loss of PI3K-Akt signaling downstream of multiple agonists, which was consistent with the result of this article that the EML4 was downregulated and PI3K/Akt/eNOS pathway was inhibited in the preeclampsia model group." (PMID 40717981, 2025).
primary cutaneous marginal zone B-cell lymphoma (1 paper, 2022). Extranodal lymphoma of lymphoid tissue associated with mucosa that is in contact with exogenous antigens. "We present a case of NSCLC harboring ALK mutation with primary cutaneous marginal zone B-cell lymphoma (PCMZL) treated with adjuvant chemotherapy with pemetrexed and cisplatin, and ALK-echinoderm microtubule-associated protein-like 4 (EML4)-targeting treatment alectinib." (PMID 36348885, 2022).
serous ovarian cancer (1 paper, 2025). "This article reports a case of EML4‐ALK‐positive advanced low‐grade serous ovarian cancer (LGSOC) with intracranial metastasis that responded dramatically to a third‐generation ALK inhibitor, lorlatinib, with good therapeutic effect." (PMID 39780907, 2025). "We report a case showing that lorlatinib is effective in treating EML4‐ALK‐positive low‐grade serous ovarian cancer (LGSO) with intracranial metastasis." (PMID 39780907, 2025). "This will become the first clinical evidence suggesting that ALK inhibitors may be an effective treatment for EML4‐ALK+ low‐grade serous ovarian cancer with intracranial metastasis." (PMID 39780907, 2025).
skin tumors (1 paper, 2024). "A recent case report described scalp skin tumors resembling an immunophenotype involving bundles of spindle cells and stromal hyalinization with an associated EML4–ALK fusion." (PMID 39202049, 2024).
small intestine cancer (1 paper, 2025). A primary or metastatic malignant neoplasm involving the small intestine. "In addition, there have been reports of EML4-ALK fusion in small intestine cancer, albeit in exceedingly rare instances, accounting for a mere 0.3%." (PMID 40160872, 2025).
triple-negative breast carcinoma (1 paper, 2015). An invasive breast carcinoma which is negative for expression of estrogen receptor (ER), progesterone receptor (PR), and human epidermal growth factor receptor 2 (HER2). "There is only one study published to date addressing triple negative breast cancers and did not report EML4-ALK rearrangement in 65 cases tested using FISH." (PMID 26312204, 2015).
tuberculosis (1 paper, 2015). A chronic, recurrent infection caused by the bacterium Mycobacterium tuberculosis. "The findings above showed that EML4-ALK fusion gene-related carcinogenesis might be different from chronic inflammation induced by smoking or tuberculosis." (PMID 25706305, 2015).
venous thromboembolism (1 paper, 2024). Occlusion of the lumen of a vein by a thrombus that has migrated from a distal site via the blood stream. "Accumulating evidence links the echinoderm microtubule-associated protein-like 4 (EML4)-anaplastic lymphoma kinase (ALK) rearrangement to venous thromboembolism (VTE) in non-small cell lung cancer (NSCLC) patients." (PMID 37940761, 2024).
tumor (233 papers, 2011 to 2025). "An hourpost-injection (p.i.), 87% of the total radioactivity in plasma originatedfrom intact [methylpiperazine-11C]brigatinib.Significant differences in tumor uptake were observed between theendogenously EML4–ALK mutated H2228 and the control xenograftA549." (PMID 37647220, 2023). "Patients harbouring multiple EML4‐ALK variants implied a poor prognosis due to the high heterogeneity in the tumour tissue." (PMID 36423218, 2023). "We and others reported similar results for the detectability of tumor DNA by genomic markers (i.e., mutations, EML4-ALK fusion or t-MAD scores)." (PMID 36461127, 2022). "Then, an ALK positive cell line, H3122 (EML4-ALK variant 1), or a patient-derived tumor from EML4-ALK-rearranged (EML4-ALK variant 1) NSCLC patient was transplanted in NSG mice." (PMID 36185084, 2022). "It revealed that the tumor harbored an echinoderm microtubule-associated protein-like 4 (EML4) and ALK fusion gene." (PMID 34064158, 2021). "An AGK‐BRAF fusion was newly identified in tumor from a donor with a known echinoderm microtubule‐associated protein‐like 4 to anaplastic lymphoma kinase (EML4‐ALK) fusion and history of anaplastic lymphoma kinase (ALK) inhibitor therapy." (PMID 31747139, 2020). "Fusion-circRNA (F-circRNA) has been reported to have tumor-promoting properties in vivo, functioning as a diagnostic marker for the EML4/ALK1 gene fusion mutation in LC40." (PMID 32071550, 2020). "About 4% of patients with NSCLC have a specific chromosomal rearrangement that generates a tumor-specific fusion gene between the EML4 gene (echinoderm microtubule-associated protein-like 4′) and the ALK gene (anaplastic lymphoma kinase)." (PMID 31911803, 2019). "Recently, we demonstrated that F-circEA-4a, a tumor-promoting circular RNA (circRNA) generated from the back-splicing of EML4-ALK variant 3b (v3b), is a novel liquid biopsy biomarker for NSCLC." (PMID 30236141, 2018). "We extended this analysis a step further by looking at the size distribution of tumor-associated EML4-ALK fusion fragments relative to germline cfDNA." (PMID 28448587, 2017). "Historically the coexistence of EGFR mutations and EML4-ALK rearrangements in the same tumor has been described as virtually impossible." (PMID 28938691, 2017). "EGFR inhibitors are approved for EGFR mutation positive tumours and anaplastic lymphoma kinase inhibitors are approved for EML4-ALK fusion positive tumours." (PMID 26905262, 2016). "Two secondary mutations, L1196M and C1156Y, within the kinase domain of EML4-ALK in tumor cells were reported in a patient during the relapse phase of treatment with an ALK inhibitor." (PMID 25888090, 2015). "Molecular analysis for K-ras mutation and the EML4-ALK fusion gene were also performed on the tumour resection specimen from 2006." (PMID 25788996, 2015). "It was also interesting to find that high abundance of EML4-ALK positive cells in tumor tissues were more common in Variant 3a+3b (4/5, 80%) than Variant 1 (1/3, 33.3%)." (PMID 23951022, 2013). "Variants 3a+3b (4/5, 80%) of EML4-ALK fusion gene were more common to have high abundance of EML4-ALK positive cells in tumor tissues than variant 1 (1/3, 33.3%)." (PMID 23951022, 2013). "When compared with the variant type data, high abundance of EML4-ALK positive cells in tumor tissues were more common in Variant 3a+3b (4/5, 80%) than Variant 1 (1/3, 33.3%)." (PMID 23951022, 2013). "The intracellular kinase domain of ALK fuses with the N-terminal of EML4, and then encodes a cytoplasmic chimeric protein with kinase activity, which subsequently drives tumor growth." (PMID 23109866, 2012). "In this patient who developed resistance to crizotinib after 5 months of treatment, molecular analyses showed the tumor had two acquired mutations within the kinase domain of EML4-ALK, C1156Y, and the gatekeeper mutation L1196M." (PMID 25031955, 2012).
tumor (continued). "We report a case of advanced PMEC, a female patient with high-grade tumor tissue differentiation and EML4-ALK fusion variants E20:A20 (V2), who was in treating with lorlatinib as the first line therapy and observed progression-free survival (PFS) over 14 months as of June 8, 2024." (PMID 39267825, 2024). "Crizotinib is a tyrosine kinase inhibitor with demonstrated effectiveness against echinoderm microtubule-associated protein-like 4 (EML4)-ALK rearrangements as well as anti-tumour activity against biologically similar domains of ROS1 and another proto-oncogene receptor tyrosine kinase, MET." (PMID 34715804, 2021). "Importantly, clone end analysis of the 2,281-independent tumor-associated EML4-ALK fusion fragments from four independent patients showed a nucleotide position bias profile similar to germline cfDNA." (PMID 28448587, 2017). "This patient’s tumor contained an EML4-ALK variant 3a fusion, which has been reported to be relatively resistant to targeted therapy compared to other ALK fusion variants, and failed to respond to both crizotinib and the second-generation ALK inhibitor, ceritinib." (PMID 28763012, 2017). "This might indicate a mixed tumor cell population or duplication of the fusion gene with gain of an ALK mutation in one of the two copies of the EML4-ALK fusion gene." (PMID 27045755, 2016). "Thus, our results indicate that EML4-ALK-mediated stem-like phenotypes are dependent on the ALK activity and anti-tumor effects caused by crizotinib treatment at least partially are related with loss of stem-like potentials in EML4-ALK+ NSCLC cells." (PMID 26517679, 2015). "To correlate the EML4-ALK fusion gene with the NSCLC profile (including smoking status, gender, tumor types, stage and ethnic characteristics) and ascertain the relationship of EML4-ALK with EGFR and KRAS mutations, we performed the present meta-analysis of 6950 patients from 27 studies." (PMID 25706305, 2015). "In NSCLC, primary resistance mechanism of ALK-fusion positive tumours has been mostly secondary mutations within the kinase domain of EML4-ALK, either when compromising drug binding (L1196M, G1269A) or when affecting enzyme conformation and activity (C1156Y, I1171T)." (PMID 25874976, 2015). "In summary, among the three detection methods for ALK rearrangements, RT-PCR could detect not only the presence of EML4-ALK fusion gene and the variant types, but also the abundance of EML4-ALK positive cells in NSCLC tumor tissues." (PMID 23951022, 2013). "One future step could also be the enrichment of prognostic algorithms with molecular tumor features, such as the presence of the shorter and more oncogenic EML4-ALK fusion variant 3, which has been associated with earlier intracranial progression in TKI-treated ALK+ NSCLC." (PMID 37988952, 2023). "To investigate the stroma-mediated drug sensitivity of NSCLC tumor cells, we established 3D cultures of EML4-ALK translocation carrying H2228 (E6; A20) and H3122 (E13; A20) cells with and without CAFs." (PMID 40524253, 2025). "Next-generation sequencing of the tumor biopsy specimen detected an EML4-ALK gene fusion (abundance, 7.88%; average sequencing depth of target regions, 3,046.34)." (PMID 40416876, 2025). "In conclusion, our findings indicate that BCL2 targeting with ABT-199, in combination with ALKi, can significantly reduce tumor cell survival in Ba/F3 EML4-ALK cell models." (PMID 39836700, 2025). "We treated control, H1322, and LA tumor cells with alectinib in vitro and found that tumor cells with LA fusion were significantly more resistant than H1322 cells with EML4‐ALK fusion." (PMID 40151836, 2025).